SEC24D (SEC24 homolog D, COPII component)
Description:
Component of the coat protein complex II (COPII) which promotes the formation of transport vesicles from the endoplasmic reticulum (ER). The coat has two main functions, the physical deformation of the endoplasmic reticulum membrane into vesicles and the selection of cargo molecules for their transport to the Golgi complex. Plays a central role in cargo selection within the COPII complex and together with SEC24C may have a different specificity compared to SEC24A and SEC24B. May more specifically package GPI-anchored proteins through the cargo receptor TMED10. May also be specific for IxM motif-containing cargos like the SNAREs GOSR2 and STX5.
Synonyms: KIAA0755; CLCRP2
Tractability: Antibody: UniProt places it where antibodies can reach, with medium confidence. PROTAC: ubiquitination databases record sites on it; its protein half-life has been measured.
Gene: Protein-coding gene on chromosome 4 (118,722,822 to 118,838,683, reverse strand). Ensembl gene ENSG00000150961.
Subcellular location: Cytoplasmic vesicle, COPII-coated vesicle membrane; Endoplasmic reticulum membrane; Cytoplasm, cytosol
Subcellular location (Human Protein Atlas): Vesicles
Pathways (Reactome):
Immune System: Antigen Presentation: Folding, assembly and peptide loading of class I MHC; MHC class II antigen presentation
Vesicle-mediated transport: COPII-mediated vesicle transport; Cargo concentration in the ER
Disease: SARS-CoV-2 activates/modulates innate and adaptive immune responses
Metabolism: Regulation of cholesterol biosynthesis by SREBP (SREBF)
Gene Ontology:
Molecular function: protein binding; SNARE binding; zinc ion binding
Biological process: COPII-coated vesicle cargo loading; endoplasmic reticulum to Golgi vesicle-mediated transport; positive regulation of ER to Golgi vesicle-mediated transport; intracellular protein transport
Cellular component: COPII vesicle coat; cytosol; endoplasmic reticulum; endoplasmic reticulum membrane; ER to Golgi transport vesicle membrane
Genetic constraint (gnomAD): Loss-of-function variants: 49 observed, 81.14 expected, observed/expected ratio (o/e) 0.6, 90% interval 0.48 to 0.77. The upper end of that interval is the gene's LOEUF score, 0.77, which puts it in group 3 of 6, group 1 being the genes least tolerant of losing a copy. Missense variants: 845 observed, 1,004.3 expected, observed/expected ratio (o/e) 0.84, 90% interval 0.79 to 0.89. Synonymous variants: 317 observed, 360.92 expected, observed/expected ratio (o/e) 0.88, 90% interval 0.8 to 0.96.
Homologues: Orthologues: chimpanzee SEC24D (99% identical), macaque SEC24D (98% identical), pig SEC24D (93% identical), dog SEC24D (92% identical), rabbit SEC24D (89% identical), mouse Sec24d (88% identical), rat Sec24d (88% identical), guinea pig SEC24D (82% identical), tropical clawed frog sec24d (67% identical), zebrafish sec24d (65% identical), Drosophila melanogaster Sec24CD (44% identical), Caenorhabditis elegans sec-24.1 (38% identical). Paralogues in human: SEC24B (27% identical), SEC24A (26% identical).
Diseases named in the same sentence as SEC24D in open-access papers:
SEC24D is named in the same sentence as 17 diseases in open-access papers, as found by Europe PMC text mining. Sharing a sentence is not in itself a finding about the gene and the disease. The quoted sentences say what the papers report.
osteogenesis imperfecta (5 papers, 2017 to 2025). Osteogenesis imperfecta (OI) comprises a heterogeneous group of genetic disorders characterized by increased bone fragility, low bone mass, and susceptibility to bone fractures with variable severity. "Similarly, mutations in SEC24D cause a syndromic form of osteogenesis imperfecta in humans, due to inefficient procollagen export from the ER." (PMID 31636606, 2019). "Mutations in Sec24D cause osteogenesis imperfecta (OI), suggesting that Sec24D is involved in collagen secretion." (PMID 39101946, 2024). "SEC24D deficiency leads to an autosomal-recessive syndromic form of osteogenesis imperfecta and autosomal-recessive Cole-Carpenter syndrome 2 (OMIM 616294), due to impaired SEC24D-dependent procollagen export from the ER." (PMID 40131364, 2025).
Cole-Carpenter syndrome (2 papers, 2021 to 2022). "SEC24D was reported to play a role in in vesicle trafficking and mutations in this gene are associated with Cole-Carpenter syndrome, a disorder affecting bone formation." (PMID 36539902, 2022).
craniosynostosis (2 papers, 2021 to 2022). Craniosynostosis is defined as the premature fusion of one or more cranial sutures leading to secondary distortion of skull shape resulting in skull deformities with a variable presentation. "Bone fragility, craniosynostosis, ocular proptosis, hydrocephalus, and distinctive facial features including frontal bossing, midface hypoplasia, and micrognathia are a typical hallmark of Cole-Carpenter syndrome-2 (CLCRP2) (MIM# 616294), due to biallelic variants in SEC24D." (PMID 35096710, 2021).
breast carcinoma (1 paper, 2019). "This indicates that SEC24D expression is a risk factor for prognosis in patients with breast cancer." (PMID 33817210, 2019). "The SEC24D gene has a high expression in breast cancer tissues and its expression level was related to the prognosis of breast cancer patients." (PMID 33817210, 2019). "The mRNA expression of the SEC24D gene in breast cancer tissues was significantly higher than that of breast normal tissues from the UALCAN database (P < 0.05)." (PMID 33817210, 2019). "This study then collected and analyzed common data sets in the UALCAN database to understand the expression and clinical significance of the SEC24D gene in breast cancer." (PMID 33817210, 2019). "Survival analysis showed that the relapse-free survival of breast cancer patients with a higher expression of SEC24D gene was significantly worse than those patients with a lower expression of SEC24D (P < 0.05)." (PMID 33817210, 2019). "In this study, we deeply explored the gene expression profile data of breast cancer and found that the expression of the SEC24D gene in breast cancer tissues was significantly higher than that in adjacent tissues." (PMID 33817210, 2019). "The survival data by Kaplan-Meier method showed that the disease-free survival of breast cancer patients with a high expression of the SEC24D gene was significantly worse than that of low-expression patients, that is, the prognosis of patients with low expression was better." (PMID 33817210, 2019).
colon cancer (1 paper, 2021). "These DEGs, significantly altered in human colon cancer tissue (TCGA) (Supplemental S4), are ones with both emerging roles (SEC24D, ABCC3, ATGL2B, and PCK2) and established roles (MYC and MUC2) in colonic tumorigenesis." (PMID 34845203, 2021). "Further, among validated DEGs were those with established roles in colon cancer and CCSC (KLF6 and SQSTM1) and those with emerging roles (SPTLC2, SEC24D, and ACACA)." (PMID 34845203, 2021).
epilepsy (1 paper, 2022). A brain disorder characterized by episodes of abnormally increased neuronal discharge resulting in transient episodes of sensory or motor neurological dysfunction, or psychic dysfunction. "A number of prioritized signals of putative pathogenicity were observed that have no reports of association with epilepsy in the literature including SEC24D, PCCA, MYO5A which may be strong candidates for further functional studies." (PMID 36539902, 2022).
insulinoma (1 paper, 2020). "Therefore, we tested whether this ERp29/Sec24D interaction was also present and perhaps relevant in Min-6 insulinoma cells using a co-immunoprecipitation approach." (PMID 32433667, 2020).
cancer (4 papers, 2018 to 2025). A tumor composed of atypical neoplastic, often pleomorphic cells that invade other tissues. "Pathway analysis for rituximab-resistant cell lines showed enriched proteins (CYTH1, SEC24D, VPS25, and ARFGAP3) involved in membrane trafficking, which is a pathway mediating many processes and enzyme functions that cancer cells can use to promote tumorigenesis and drug responses." (PMID 41301803, 2025).
tumor (3 papers, 2018 to 2021). "The result indicated that the expression level of SEC24D in tumor tissue was higher than its matched normal tissue in most of the tumors." (PMID 33817210, 2019). "Intracellular protein transport is also an important link affecting tumor cell viability and proliferation, and SEC24D gene is an important factor affecting protein transport, suggesting that the SEC24D gene plays an active role in tumor cells." (PMID 33817210, 2019).
infection (2 papers, 2015 to 2025). The state of being infected such as from the introduction of a foreign agent such as serum, vaccine, antigenic substance or organism. "There was about a 20% infection reduction with the combined depletion of Sec24c and Sec24d isoforms (p-value 0.0004)." (PMID 40431628, 2025). "During infection with B. abortus, the downstream targets of the IRE1 pathway Sar1, Sec23, and Sec24D, were upregulated significantly." (PMID 25742138, 2015). "Infection with B. abortus upregulated the COPII vesicle components Sar1, Sec23 and Sec24D, which might enhance the capacity of COPII vesicles to export from ERES." (PMID 25742138, 2015).
SEC24D also shares sentences with these, for which no sentence is quoted: Arrhythmogenic right ventricular dysplasia (1 paper); bacterial disease (1); congenital dyserythropoietic anemia (1); hepatitis B virus infection (1); Hydrocephalus (1); Polycystic kidney dysplasia (1); Vici syndrome (1).